KIF20A (kinesin family member 20A)
Diseases named in the same sentence as KIF20A in open-access papers (continued):
Sharing a sentence is not in itself a finding about the gene and the disease.
glioma (continued). "Then, we demonstrated that GSC23 cell exosome-secured circ-Serpine2 can exacerbate KIF20A expression by sponging miR-124-3p, thus promoting glioma proliferation, migration and invasion in vitro and inhibiting glioma apoptosis in vitro." (PMID 34689806, 2021). "Reducing circ-Serpine2 expression also promoted glioma apoptosis and was rescued through a miR-124-3p inhibitor or KIF20A mimics." (PMID 34689806, 2021). "Such evidence indicated that circ-Serpine2 modulates glioma malignancy through the miR-124-3p/KIF20A nexus." (PMID 34689806, 2021). "This evidence led to the conclusion that circ-Serpine2 promotes glioma cell proliferation, migration and invasion across the miR-124-3p/KIF20A nexus." (PMID 34689806, 2021). "In silico analyses identified KIF20A to be upregulated within gliomas, according to tumor grade, with glioma patients having upregulated KIF20A experiencing poor prognoses." (PMID 34689806, 2021). "Through circRNA sequencing and differential analysis, we found that hsa_circ_001588 (Serpine2) was highly upregulated in GSC23 compared to glioma cells, miR-124-3p was severely downregulated in glioma cells, and KIF20A was significantly upregulated in gliomas." (PMID 34689806, 2021). "Until now, KIF20A is proved to be a key point in the development and progression of many cancers, such as leukemia, ovarian cancer, glioma, non-small cell lung cancer, bladder cancer, gastric cancer, and pancreatic cancer." (PMID 31565099, 2019). "High expression of KIF20A results poor prognosis in glioma patients, nasopharyngeal cancer, hepatocellular carcinoma, melanoma and early-stage cervical squamous cell carcinoma." (PMID 30778371, 2019). "Moreover, canonical oncogenic proliferation markers MKI67 and TOP2A were upregulated in the CDC20+KIF20A+PTTG1+ cell subpopulation of glioma samples." (PMID 40047299, 2025). "Finally, we combined CDC20 and KIF20A related inhibitors Apcin and Paprotrain to performed therapy experiments in glioma PDOs." (PMID 40047299, 2025). "Hence, these results suggest that CDC20+KIF20A+PTTG1+ glioma cell subpopulation is potential target in effective TMZ‐sensitizing therapies." (PMID 40047299, 2025). "Therefore, the CDC20+KIF20A+PTTG1+ cell subpopulation featured aberrant oncogenic molecular activity in glioma, suggesting that these cells are therapeutically vulnerable to glioma progression." (PMID 40047299, 2025). "Moreover, spatial atlas of GBM also showed that relative higher hypoxia level in spots of CDC20+KIF20A+PTTG1+ glioma cell subpopulation." (PMID 40047299, 2025). "Additionally, in glioma, KIF20A depletion disrupts cell division processes, leading to decreased cell proliferation and increased apoptosis." (PMID 41392981, 2025). "Furthermore, we discovered that glioma patients exhibiting higher expression levels of KIF20A had a worse prognosis than those with lower expression levels (all p < 0.001)." (PMID 37744243, 2023). "Furthermore, this study identified the significant role of the KIF20A gene in glioma through in vitro experiments." (PMID 37744243, 2023). "KIF20A was identified as a key gene in glioma by using protein-protein interaction (PPI) network." (PMID 37744243, 2023). "In glioma-derived exosomes, bioinformatics analysis revealed that KIF20A was one of the hub genes." (PMID 36798768, 2023). "As a member of KIFs, KIF20A (also known as mitotic kinesin-like protein 2, MKlp2) was increased in cancer, including glioma, and could work as an independent prognostic factor." (PMID 36798768, 2023). "Collectively, our study suggested that KIF20A is a potential biomarker for glioma." (PMID 37744243, 2023). "Serpine2 was identified as an oncogenic agent in GSCs, which could be transported to glioma cells to enhance their tumorigenicity by regulating the miR-124-3p/KIF20A axis." (PMID 36321132, 2022). "This study identified circ-Serpine2/miR-124-3p/KIF20A as a regulatory pathway in glioma." (PMID 34689806, 2021).
glioma (continued). "In our signaling pathway regulation experiment, we found that the silencing of circ-Serpine2 could increase miR-124-3p expression and decrease KIF20A expression in glioma cells." (PMID 34689806, 2021). "This investigation identified that KIF20A showed significantly high expression in glioma tissues, which suggested that this hub gene could have an essential place for exacerbating glioma expansion." (PMID 34689806, 2021). "Moreover, KIF20A was also reported as a prognostic indicator for cervical squamous cell carcinoma, ovarian clear‐cell carcinoma, and glioma 37-39." (PMID 33403046, 2021). "CircRNA-Serpine2 upregulates KIF20A expression by sponging miR-124–3p within gliomas." (PMID 34689806, 2021). "Recently, it has been suggested that targeting KIF20A by immunotherapy may have potential therapeutic efficacy in glioma." (PMID 32963620, 2020). "Patients with gliomas and a high KIF20A expression have a poor prognosis." (PMID 31093305, 2019). "To date, KIF20A has been found to be highly expressed in various tumors such as cervical squamous cell carcinoma, ovarian clear-cell carcinoma, hepatocellular carcinoma, gastric cancer, bladder cancer, and glioma." (PMID 31565099, 2019). "Additionally, we identified KIF20A as a prognostic and therapeutic biomarker for glioma." (PMID 37744243, 2023). "In the treatment of glioma, KIF20A could become the target of miR-876-3p." (PMID 36798768, 2023). "Nevertheless, the role and mechanism of KIF20A in glioma remain unclear." (PMID 37744243, 2023). "In addition, despite the preliminary functional investigation of the KIF20A in this study, its precise mechanism of action in glioma remains unclear, demanding further comprehensive research to clarify its molecular mechanism." (PMID 37744243, 2023). "Moreover, KIF20A blockade led to enhanced apoptotic activity within SF126 glioma cells." (PMID 34689806, 2021). "In addition, they found that KIF20A might play a key role in the chemotherapy resistance of gliomas." (PMID 31565099, 2019). "In addition, KIF20A is highly expressed in glioma cell lines and glioma tissues." (PMID 31093305, 2019). "CDC20, KIF20A and PTTG1 remained co‐expressed in glioma cells, and this cell subpopulation was increased in four recurrence glioma cases under therapy." (PMID 40047299, 2025). "This subgroup is naturally present at high grades and shows more CDC20+KIF20A+PTTG1+ cells than LGG, suggesting a critical role in glioma progression." (PMID 40047299, 2025). "Another KIF20A co-expressed gene, CCNA2, its overexpression in glioma results in a significant cell proliferation rate and activate G2M checkpoint pathways." (PMID 39624268, 2024). "A trial using a polypeptide vaccine targeting LY6K, DEPDC1, KIF20A, and FOXM1 in patients with high-grade glioma showed that the vaccine was well tolerated, elicited an effective immune response, and prevented disease progression for at least 6 months." (PMID 39727968, 2024). "We found that the KIF20A gene was downregulated in the PBT030 and PBT147 lines upon treatment of glioma cells with ICG-001." (PMID 38449858, 2024). "CDC20, KIF20A and PTTG1 were specifically co‐expressed in Bio‐C8 LGG glioma cells." (PMID 40047299, 2025). "Impressively, CDC20, KIF20A and PTTG1 were naturally and highly co‐expressed in GBM glioma cells." (PMID 40047299, 2025). "Then, a series of phenotypic assays were performed to investigate whether CDC20, KIF20A and PTTG1 knockdown inhibits proliferation phenotypes in glioma cell lines." (PMID 40047299, 2025). "KIF20A is emerging as an oncogene, being widely expressed in tumor tissues and potentially contributing to cell growth and tumor metastasis by interacting with JAK-STAT3 pathway in colorectal cancer and glioma." (PMID 39624268, 2024). "Positive expression of KIF20A correlates with a poor prognosis and tumour growth and progression in early-stage of several types of cancer including breast, colorectal and cervical cancers but also PDAC and glioma." (PMID 36998446, 2023).
glioma (continued). "Finally, we have identified and experimentally validated a glycolysis-related key gene, kinesin family member 20A (KIF20A), which serves as a prognostic biomarker and therapeutic target for glioma." (PMID 37744243, 2023). "Downregulation of KIF20A decreased cellular proliferative properties within gliomas through lack of cytokinesis binucleated cell development." (PMID 34689806, 2021). "Kinesin family member 20A (KIF20A) is believed to modulate microtubule dynamics, which could promote the tumorigenesis and progression of prostate cancer and glioma, particularly the biochemical recurrence and metastasis." (PMID 34384030, 2021). "Our result showed that KIF20A expression in LUAD was highly positively correlated with Ki‐67 level, bearing similarities with observations from Duan et al11 who reported that the expression of KIF20A was relevant to Ki67 expression in gliomas." (PMID 30105795, 2018). "Consistent with ICG-001-induced differentiation of PBT147 and PBT030 lines, ICG-001 treatment led to a significant reduction in the expression of KIF20A, as measured by qPCR, further confirming that the differentiating effects of ICG-001 on glioma lines are not cell line dependent." (PMID 38449858, 2024).
bladder cancer (29 papers, 2011 to 2026). "Patients with bladder cancer who have high tumor-evaluated stages that are advanced and have poor outcomes are linked to high KIF20A expression." (PMID 39911278, 2025). "Tianyu Shen’s findings reveal a significant upregulation of KIF20A in bladder cancer, associated with increased proliferation and metastasis, marking it as a crucial prognostic factor and therapeutic target." (PMID 39272816, 2024). "Our results seem to be in accordance with previous investigations reporting an association between KIF20A expression and advanced pathological parameters in bladder cancer and gastric cancer." (PMID 39624268, 2024). "Overexpression of KIF20A has been associated with increased tumor growth, invasion, and metastasis in bladder cancer." (PMID 37310408, 2023). "The expression of KIF20A was significantly associated with the degree of pathological differentiation of bladder cancer." (PMID 31093305, 2019). "Inhibition of KIF20A helps to soften the intracellular environment in both high- and low-grade bladder cancer." (PMID 36980610, 2023). "Another study found that KIF20A was involved in the resistance of bladder cancer cells to chemotherapy drugs." (PMID 37310408, 2023). "Research suggests that KIF20A is overexpressed in bladder cancer cells, meaning that there is an abnormally high amount of the protein in these cells." (PMID 37310408, 2023). "kIF20A (kinesin family member 20A), was shown to promote proliferation and metastasis of bladder cancer cells, and bladder cancer patients with high expression of KIF20A had poorer tumor differentiation and poorer prognosis." (PMID 37051238, 2023). "The expression of KIF20A is relatively high in bladder cancer tissues, and patients with a high expression of KIF20A have a poor prognosis and a high rate of metastasis." (PMID 36980610, 2023). "Knockdown of KIF20A inhibits cell migration and proliferation in bladder cancer and prostate cancer." (PMID 36980610, 2023). "Study has indicated that a poor prognosis was related to the patients with a high KIF20A expression in bladder cancer and a high KIF18B expression in lung adenocarcinoma." (PMID 34112092, 2021). "The role of KIF20A in numerous tumors has been previously reported, such as bladder cancer, lung adenocarcinoma, renal clear cell carcinoma has been previously reported 67-70." (PMID 33995639, 2021). "KIF20A can affect the prognosis of bladder cancer by promoting the proliferation and metastasis of bladder cancer cells.KIF20A." (PMID 33941190, 2021). "It has been reported that patients with bladder cancer with high expression of KIF20A have poorer tumor stages and that KIF20A promotes metastasis and proliferation of bladder cancer cells." (PMID 33912448, 2021). "KIF20A is a mitotic kinase that affects the prognosis of bladder cancer by promoting the proliferation and metastasis of bladder cancer cells." (PMID 33519918, 2020). "Based on our knowledge of the current scientific research, this is the first report on KIF20A in bladder cancer." (PMID 31093305, 2019). "Many studies have found that the upregulation of KIF20A is associated with cancer, but the development and potential molecular mechanisms of KIF20A in bladder cancer are not well understood." (PMID 31093305, 2019). "The preliminary results indicated that both the transcriptional and translational KIF20A expression levels were increased in bladder cancer." (PMID 31093305, 2019). "The effect of the KIF20A expression on the proliferation of bladder cancer cells was evaluated by a mouse xenograft model." (PMID 31093305, 2019). "The survival rate of patients with bladder cancer with a high KIF20A expression was significantly lower than that of patients with bladder cancer with a low KIF20A expression (P = 0.012)." (PMID 31093305, 2019). "The effects of KIF20A on the proliferation and invasion of bladder cancer cells were detected in vitro and in vivo." (PMID 31093305, 2019).
bladder cancer (continued). "According to the analysis of TCGA data, the high KIF20A expression in bladder cancer patients leads to a decrease in disease-free survival." (PMID 31093305, 2019). "We believe that knocking down KIF20A can effectively reduce the invasion ability of bladder cancer cells." (PMID 31093305, 2019). "We studied the relationship between the expression of KIF20A and the clinicopathological features and prognosis of bladder cancer." (PMID 31093305, 2019). "The effect of the differential expression of KIF20A on the prognosis of patients with bladder cancer was analysed by the TCGA database." (PMID 31093305, 2019). "Our group will continue to explore the molecular mechanism of KIF20A in the development of bladder cancer." (PMID 31093305, 2019). "The results showed that the protein levels of KIF20A in the bladder cancer cell lines were higher than those in the normal bladder cell line." (PMID 31093305, 2019). "At present, research on the effect of KIF20A on the proliferation, invasion, and migration of bladder cancer cells is still in the preliminary stage, and the specific regulation and mechanisms of KIF20A have yet to be studied." (PMID 31093305, 2019). "Bladder cancer patients with a high KIF20A expression have a worse tumour differentiation and a poor prognosis." (PMID 31093305, 2019). "In this study, we examined the expression of KIF20A in clinical specimens of bladder cancer and found that the expression of KIF20A in the bladder cancer tissues is higher than that in the adjacent tissues." (PMID 31093305, 2019). "First, we used western blot to detect the protein expression levels of KIF20A in the bladder cancer cell lines T24, BIU87, EJ, and 5637 and in the normal bladder cell line SV-HUC-1." (PMID 31093305, 2019). "According to the results of the immunohistochemical scoring, the positive rate of the KIF20A expression in bladder cancer tissues was 67.6% (17.9% strong positive, 49.7% weak positive)." (PMID 31093305, 2019). "The relationship between the KIF20A expression and the clinical pathology of bladder cancer was analysed." (PMID 31093305, 2019). "The MTT assay further tested the effect of knocking down KIF20A on the proliferation of the bladder cancer cell lines T24/5637." (PMID 31093305, 2019). "We further explored the effect of KIF20A on the biological function of bladder cancer cells in vitro." (PMID 31093305, 2019). "Since the protein expression level of KIF20A was higher in T24 and 5637 cell lines than in the other bladder cancer cell lines, we chose these two cell lines for experimental studies." (PMID 31093305, 2019). "This suggests that the high KIF20A expression indicates a poor prognosis in patients with bladder cancer." (PMID 31093305, 2019). "We further analysed the relationship between the KIF20A expression and the clinical pathology of bladder cancer." (PMID 31093305, 2019). "The expression of KIF20A was significantly higher in the bladder cancer tissues than in the adjacent control tissues." (PMID 31093305, 2019). "KIF20A is overexpressed in bladder cancer and renal cell carcinoma and may play a role in the development and progression of these cancers." (PMID 37310408, 2023). "Several studies have investigated the relationship between KIF20A and bladder cancer." (PMID 37310408, 2023). "Interestingly, several studies showed a correlation between KIF20A overexpression and tumor progression and proliferation in colorectal cancer, renal clear cell carcinoma, and bladder cancer cells." (PMID 35322101, 2022). "Firstly, the KIF20A gene probe was found to have the top spot for downregulated genes after Co2B NPs, and according to the recent analysis, the KIF20A gene was found to have a metastatic and proliferative impact on bladder cancer in vitro." (PMID 36500178, 2022).